ISCU (iron-sulfur cluster assembly enzyme)
Description:
[Isoform 1]: Mitochondrial scaffold protein, of the core iron-sulfur cluster (ISC) assembly complex, that provides the structural architecture on which the [2Fe-2S] clusters are assembled. The core iron-sulfur cluster (ISC) assembly complex is involved in the de novo synthesis of a [2Fe-2S] cluster, the first step of the mitochondrial iron-sulfur protein biogenesis. This process is initiated by the cysteine desulfurase complex (NFS1:LYRM4:NDUFAB1) that produces persulfide which is delivered on the scaffold protein ISCU in a FXN-dependent manner. Then this complex is stabilized by FDX2 which provides reducing equivalents to accomplish the [2Fe-2S] cluster assembly. Finally, the [2Fe-2S] cluster is transferred from ISCU to chaperone proteins, including HSCB, HSPA9 and GLRX5 (Probable). Exists as two slow interchanging conformational states, a structured (S) and disordered (D) form. May modulate NFS1 desulfurase activity in a zinc-dependent manner. Modulates the interaction between FXN and the cysteine desulfurase complex. [Isoform 2]: Cytoplasmic scaffold protein, of the cytoplasmic core iron-sulfur cluster (ISC) assembly complex that provides the structural architecture on which the Fe-S clusters are assembled and may be involved in the cytoplasmic iron-sulfur protein biogenesis.
Synonyms: NIFUN; ISU2; hnifU; 2310020H20Rik; HML; NIFU
Tractability: Small molecule: a structure with a bound ligand is known. PROTAC: ubiquitination databases record sites on it; its protein half-life has been measured.
Gene: Protein-coding gene on chromosome 12 (108,562,582 to 108,569,380, forward strand). Ensembl gene ENSG00000136003.
Subcellular location: Mitochondrion (Isoform 1); Cytoplasm (Isoform 2); Nucleus
Subcellular location (Human Protein Atlas): Cytosol; Mitochondria
Pathways (Reactome):
Metabolism: Complex III assembly; Maturation of TCA enzymes and regulation of TCA cycle; Mitochondrial iron-sulfur cluster biogenesis
Disease: Maturation of replicase proteins
Gene Ontology:
Molecular function: ferrous iron binding; iron-sulfur cluster chaperone activity; molecular adaptor activity; protein binding; protein homodimerization activity; zinc ion binding; 2 iron, 2 sulfur cluster binding; iron ion binding; iron-sulfur cluster binding
Biological process: [2Fe-2S] cluster assembly; [4Fe-4S] cluster assembly; intracellular iron ion homeostasis; negative regulation of iron ion import across plasma membrane; positive regulation of mitochondrial electron transport, NADH to ubiquinone; iron-sulfur cluster assembly
Cellular component: cytoplasm; cytosol; mitochondrial [2Fe-2S] assembly complex; mitochondrion; nucleus; iron-sulfur cluster assembly complex; mitochondrial matrix
Genetic constraint (gnomAD): Loss-of-function variants: 8 observed, 9.24 expected, observed/expected ratio (o/e) 0.87, 90% interval 0.51 to 1.54. That is too few expected variants to judge how well the gene tolerates losing a copy. Missense variants: 190 observed, 160.93 expected, observed/expected ratio (o/e) 1.18, 90% interval 1.05 to 1.33. Synonymous variants: 86 observed, 71.73 expected, observed/expected ratio (o/e) 1.2, 90% interval 1.01 to 1.43.
Gene-disease validity (ClinGen):
ClinGen rates the evidence that ISCU causes each of these diseases.
mitochondrial disease (autosomal recessive): Definitive.
Homologues: Orthologues: macaque ISCU (99% identical), dog ISCU (99% identical), rabbit ISCU (99% identical), guinea pig ISCU (98% identical), mouse Iscu (97% identical), rat Iscu (97% identical), pig ISCU (92% identical), zebrafish iscua (76% identical), zebrafish iscub (72% identical), tropical clawed frog iscu (70% identical), Drosophila melanogaster IscU (68% identical), Caenorhabditis elegans iscu-1 (59% identical).
Diseases named in the same sentence as ISCU in open-access papers:
ISCU is named in the same sentence as 15 diseases in open-access papers, as found by Europe PMC text mining. Sharing a sentence is not in itself a finding about the gene and the disease. The quoted sentences say what the papers report.
cervical cancer (2 papers, 2024). A primary or metastatic malignant neoplasm involving the cervix. "Finally, combining the analysis results with a literature review, we found that the Iron-Sulfur Cluster Assembly Enzyme (ISCU) gene has good predictive value in the prognosis and diagnosis of cervical cancer." (PMID 38840928, 2024).
iron deficiency (2 papers, 2018 to 2025). "Mechanistically, chronic hypoxia-mediated iron deficiency enhances HIF2α activation, subsequently suppressing iron/sulfur cluster assembly enzyme (ISCU) expression." (PMID 40427635, 2025). "To further proof that the decrease of Fxn and IscU was not simply due to iron deficiency, we examined whether overexpression of TfR1 would improve the mitochondrial function in Irp1−/− and Irp2−/− cells." (PMID 29572489, 2018).
breast carcinoma (1 paper, 2021). "And there was a co-expression relationship between AC108474.1 and 5 ferroptosis-related genes (TAZ, ISCU, CAV1, PLIN4, and HIC1), including 1 ferroptosis driver, 2 ferroptosis suppressor and 2 ferroptosis marker, and AC108474.1 was a protective factor for breast cancer patients too." (PMID 34164433, 2021).
cyst (1 paper, 2023). A sac-like closed membranous structure that may be empty or contain fluid or amorphous material. "Interestingly, the function of Grx5 and BolA1 may be stage-specific in G. intestinalis as their genes together with IscU are significantly upregulated at the cyst stage." (PMID 37792908, 2023).
Friedreich ataxia (1 paper, 2014). An inherited condition that affects the nervous system and causes movement problems. "Mutations in Fe-S proteins often disrupt Fe-S cluster assembly leading to a spectrum of severe disorders such as Friedreich's ataxia or iron-sulfur cluster assembly enzyme (ISCU) myopathy." (PMID 24498631, 2014).
lactic acidosis (1 paper, 2025). Metabolic acidosis characterized by the accumulation of lactate in the body. "Hereditary myopathy with lactic acidosis due to Iron-Sulfur Cluster Assembly Enzyme (ISCU) deficiency is a rare disorder of energy metabolism characterized clinically by myopathy with exercise intolerance, and biochemically by deficiencies of skeletal muscle mitochondrial respiratory chain enzymes." (PMID 40529812, 2025).
multiple sclerosis (1 paper, 2024). A progressive autoimmune disorder affecting the central nervous system resulting in demyelination. "This study identified IREB2, LAMP2, ISCU, ATP6V1G1, ATP13A2, and SKP1 as genes associated with multiple sclerosis (MS) and iron metabolism, establishing their multi-gene diagnostic value for MS with an AUC of 0.83." (PMID 38590521, 2024).
oropharyngeal squamous cell carcinoma (1 paper, 2019). "The HIF-1α-driven overexpression of glycolytic enzymes and miR-210 is coupled to the downregulation of its target iron-sulfur cluster assembly enzyme (ISCU) in oropharyngeal squamous cell carcinoma (OPSCC)." (PMID 31416244, 2019).
preeclampsia (1 paper, 2018). Preeclampsia is a hypertensive disorder of pregnancy that is characterized by new-onset hypertension with proteinuria presenting after 20 weeks of gestation, and depending on mild or severe forms may initially present with severe headache, visual disturbances, and hyperreflexia. "A placental mRNA/miRNA network involving microRNA (miR)-210, iron sulfur-cluster assembly enzyme (ISCU) and HIF1α was proposed to regulate mitochondrial function during preeclampsia." (PMID 29316938, 2018).
tumor (8 papers, 2010 to 2024). "ISCU is a gene associated with ferroptosis, and the downregulation of this gene in tissue is generally beneficial to tumor growth, which is consistent with the results of this study." (PMID 36057587, 2022). "For instance, ISCU, a target gene of miR‐210, demonstrated an inverse link with prognosis and was down‐regulated by miR‐210 in vivo, leading to tumour development." (PMID 38534098, 2024). "According to the analysis of the TCGA data, the expression of MIPEP and NFS1 was higher in tumor tissues in comparison with that in normal tissues; however, the expression of CPT2 and ISCU was lower in tumor tissues in relative to that in normal tissues." (PMID 36776001, 2023). "In human cancer cell lines and tumours, we found that miR-210 targets the mitochondrial iron sulfur scaffold protein ISCU, required for assembly of iron-sulfur clusters, cofactors for key enzymes involved in the Krebs cycle, electron transport, and iron metabolism." (PMID 20436681, 2010). "Downregulation of the Fe/S cluster protein assembly -ISCU (iron-sulfur cluster assembly enzyme) by miR-210 induces Reactive Oxygen Species (ROS) production in hypoxia, a preferential shift to glycolysis, increased lactate production, and enhanced cell survival in tumor cells." (PMID 37810966, 2023).
ISCU also shares sentences with these, for which no sentence is quoted: cancer (5 papers); myopathy (2); colon cancer (1); COVID-19 (1); glioma (1).